EGR3 (early growth response 3)
Description:
Probable transcription factor involved in muscle spindle development.
Synonyms: EGR-3; PILOT
Tractability: No criterion of Open Targets' tractability assessment is met for any kind of drug.
Gene: Protein-coding gene on chromosome 8 (22,687,659 to 22,693,480, reverse strand). Ensembl gene ENSG00000179388.
Subcellular location: Nucleus
Subcellular location (Human Protein Atlas): Nucleoplasm; Vesicles
Pathways (Reactome):
Signal Transduction: NGF-stimulated transcription
Gene Ontology:
Molecular function: sequence-specific double-stranded DNA binding; DNA-binding transcription factor activity; DNA-binding transcription factor activity, RNA polymerase II-specific; RNA polymerase II cis-regulatory region sequence-specific DNA binding; DNA-binding transcription activator activity, RNA polymerase II-specific; sequence-specific DNA binding
Biological process: cell migration involved in sprouting angiogenesis; cellular response to fibroblast growth factor stimulus; cellular response to vascular endothelial growth factor stimulus; endothelial cell chemotaxis; negative regulation of apoptotic process; positive regulation of endothelial cell proliferation; circadian rhythm; muscle organ development; regulation of transcription by RNA polymerase II; positive regulation of transcription by RNA polymerase II; system development
Cellular component: chromatin; nucleoplasm; nucleus
Genetic constraint (gnomAD): Loss-of-function variants: 4 observed, 23.14 expected, observed/expected ratio (o/e) 0.17, 90% interval 0.084 to 0.4. The upper end of that interval is the gene's LOEUF score, 0.4, which puts it in group 1 of 6, group 1 being the genes least tolerant of losing a copy. Missense variants: 315 observed, 570.82 expected, observed/expected ratio (o/e) 0.55, 90% interval 0.5 to 0.61. Synonymous variants: 219 observed, 241.14 expected, observed/expected ratio (o/e) 0.91, 90% interval 0.81 to 1.02.
Homologues: Orthologues: chimpanzee EGR3 (100% identical), guinea pig EGR3 (99% identical), mouse Egr3 (99% identical), pig EGR3 (99% identical), rabbit EGR3 (97% identical), dog EGR3 (89% identical), rat Egr3 (89% identical), macaque EGR3 (87% identical), zebrafish egr3 (68% identical), tropical clawed frog egr3 (68% identical). Paralogues in human: EGR2 (53% identical), EGR1 (48% identical), EGR4 (30% identical), WT1 (25% identical).
Diseases named in the same sentence as EGR3 in open-access papers:
EGR3 is named in the same sentence as 98 diseases in open-access papers, as found by Europe PMC text mining. Sharing a sentence is not in itself a finding about the gene and the disease. The quoted sentences say what the papers report.
breast cancer (23 papers, 2010 to 2025). A primary or metastatic malignant neoplasm involving the breast. "In contrast, in breast cancer cells treated with a curcumin analog, EGR3 upregulation was linked to inhibition of cell migration, implicating a tumor-suppressive role." (PMID 40649712, 2025). "The results indicated that high expression levels of OPN4, NOS2, GPR157, NCOA2, CLOCK, and TH were associated with shorter OS in breast cancer patients, while high expression of EGR3, NR1H3, RELB, SIAH2, and ADRB1 was linked to improved survival rates." (PMID 41031266, 2025). "We noted significant declines in the level of several transcripts associated with metastasis (Cd36, Egr3, and Maf) and tumorigenesis (Ccr2 and Ccr6) in many solid tumors including breast cancer." (PMID 33682324, 2021). "EGR3 was validated as a dual-function regulator of tumor suppression and immunomodulation, offering a novel therapeutic target for breast cancer, particularly in immunologically “cold” triple-negative subtypes." (PMID 41472745, 2025). "The genes most frequently affected by CNA deletions in breast cancer were EGR3 (3.8%), PEBP4 (3.7%), and TNFRSF10C (3.7%)." (PMID 40585280, 2025). "Our findings resolve this discrepancy by demonstrating context-dependent roles: In breast cancer, EGR3 downregulation correlates with advanced stages and immunosuppression, while its overexpression inhibits proliferation and enhances CTL activity." (PMID 41472745, 2025). "Future efforts should focus on translating the 3-gene signature into clinical assays and exploring EGR3-targeted combination therapies to overcome immune resistance in breast cancer." (PMID 41472745, 2025). "Prioritizing EGR3 for mechanistic validation, clinical specimen analysis confirmed significant EGR3 downregulation in breast carcinomas." (PMID 41472745, 2025). "Future research should focus on investigating the biological implications and prognostic value of EGR3 in canine mammary cancer patients." (PMID 38338065, 2024). "The results revealed a notable downregulation of AVPR1A, FEZ1, HGF, GSN, NEDD9, and EGR3 expression in the breast cancer cell lines (MCF7, BT-474, SK-BR-3, MDA-MB-231) when compared to the normal mammary epithelial cell line (MCF-10A)." (PMID 38756447, 2024). "This study revealed the anti-tumor activity of C6 ceramide in canine mammary cancer both in vivo and in vitro and revealed that EGR3 is a potential biomarker in canine mammary cancer prognosis and treatment." (PMID 38338065, 2024). "Further exploring found that EGR3 is a target agent of C6 ceramide, promoting canine mammary cancer cell proliferation and migration by activating the pJAK1/pSTAT3 signaling pathway." (PMID 38338065, 2024). "This study implicates the mechanisms underlying the anti-tumor activity of C6 ceramide and demonstrates the potential of EGR3 as a novel target for treating canine mammary cancer." (PMID 38338065, 2024). "In conclusion, C6 ceramide inhibits canine mammary cancer growth and metastasis by targeting EGR3 through the regulation of the JAK1/STAT3 signaling pathway." (PMID 38338065, 2024). "The FOS, FOSB, EGR1, and EGR3 expression levels in healthy breast tissues were higher than in breast cancer tissues." (PMID 37233869, 2023). "Egr3 is also known to be an estrogen-responsive gene that is involved in the estrogen signaling pathway in MCF7 human breast cancer cells." (PMID 24722338, 2014). "EGR3 encodes a transcriptional regulator that belongs to EGR family and has been shown to be involved in the estrogen signaling pathway in breast cancer." (PMID 24564956, 2013). "For instance, Myc, CCND1, FOS and EGR3 are well-studied ERα targets promoting breast cancer growth and progression." (PMID 22125492, 2011). "The second gene frequently altered in breast cancer is EGR3." (PMID 40585280, 2025).
breast cancer (continued). "Moreover, the functional roles of immunomodulatory molecules—particularly early growth response factors like EGR3—in breast cancer progression remain poorly defined, further restricting clinical translation." (PMID 41472745, 2025). "By functionally connecting EGR3 to both tumor suppression and cytotoxic T cell activation, we provide actionable insights for overcoming immunotherapy resistance—a critical unmet need in breast cancer management." (PMID 41472745, 2025). "However, in tamoxifen-resistant breast cancer, EGR3 was upregulated and directly promoted expression of MCL1, contributing to therapy resistance." (PMID 40649712, 2025). "Additionally, we have identified the deletion of EGR3 to be a crucial genetic alteration in canine mammary cancer, which regulates the JAK1/STAT3 signaling pathway." (PMID 38338065, 2024). "However, patients with breast cancer exhibiting upregulated expression levels of FOS, FOSB, EGR1, and EGR3 were associated with improved prognosis." (PMID 37233869, 2023). "Studies have shown that EGR3 regulates estrogen‐mediated invasion of breast cancer cells." (PMID 37102654, 2023). "IL-6 and IL-8 function as downstream targets of Egr3 in breast cancers." (PMID 34234781, 2021). "Hence, we attempted to explore the potential mechanism capable of explaining why higher expression levels of EGR1, EGR2, and EGR3 predicted better outcomes in patients with breast cancer." (PMID 33614706, 2020). "MCF7 human breast carcinoma cells have been shown to express Egr3." (PMID 24722338, 2014). "EGR3 may prove to be a valuable target for diagnosing and treating canine mammary cancer." (PMID 38338065, 2024). "Second, the expression of EGR3 in canine mammary cancer patients is unknown." (PMID 38338065, 2024). "However, the specific regulatory effect and molecular aspects of EGR3 in canine mammary cancer remain unknown." (PMID 38338065, 2024). "Therefore, we hypothesized that FOS, FOSB, EGR1, and EGR3 mainly function as tumor suppressor genes to inhibit the occurrence and progression of breast cancers." (PMID 37233869, 2023). "This study establishes a machine learning-optimized 3-gene prognostic signature (EGR3, RECQL4, MMP1) that bridges prognostic stratification and tumor-immune interplay in breast cancer, offering both clinical and mechanistic advancements." (PMID 41472745, 2025). "To investigate the mechanistic basis of the three-gene prognostic signature (EGR3, RECQL4, MMP1) in breast cancer progression, we performed differential expression analysis followed by GO and KEGG pathway enrichment analyses between the two molecular subtypes." (PMID 41472745, 2025). "We found 11 genes (2 stage-III salient genes and 9 stage-IV salient genes) annotated as ‘cancer related genes’, of which two stage-IV salient markers, namely EGR3 and KRT15, were specifically noted as prognostic markers of breast cancer." (PMID 41048341, 2025). "To elucidate the functional roles of the three prognostic signature genes (EGR3, RECQL4, and MMP1) in breast cancer pathogenesis, we conducted comprehensive multi-omics analyses across multiple datasets." (PMID 41472745, 2025). "The expression of six rhythm genes, CRY2, NFIL3, PER1, EGR3, NR1D1 and TIMELESS, was significantly changed in breast cancer compared with normal breast tissues." (PMID 35180863, 2022). "As indicated by the results, the transcriptional levels of EGR1, EGR2, and EGR3 were significantly reduced in patients with BRCA (p < 0.05), whereas the expression level of EGR4 was very low in both breast cancer and normal breast tissues." (PMID 33614706, 2020). "EGR3 is the bona fide target for ESR and involved in the estrogen-signaling pathway in breast cancer cells." (PMID 27220887, 2016).
breast cancer (continued). "We further compared the mRNA levels of these six rhythm genes between 20 normal breast tissues and 20 breast cancer tissues by using qPCR and confirmed that the aberrant expression of NFIL3 and EGR3 in breast cancer is consistent with the results from the GEPIA database." (PMID 35180863, 2022). "In all subtypes of breast cancer, the mRNA levels of EGR1, EGR2, and EGR3 were all lower in malignant breast tissues compared with normal tissues." (PMID 33614706, 2020).
schizophrenia (20 papers, 2010 to 2025). A major psychotic disorder characterized by abnormalities in the perception or expression of reality. "Among EGR genes, EGR3 has demonstrated a strong and consistent association with schizophrenia in both family-based and case–control association studies within Japan and Korea." (PMID 39518903, 2024). "We found Egr3 is enriched in neuronal maternally accessible peaks, and Egr3 is a potential susceptibility candidate in schizophrenia." (PMID 36161934, 2022). "We previously reported the genetic association of EGR3 with schizophrenia and downregulation of the transcripts for EGR1, EGR2, and EGR3 in the postmortem brain samples from patients with schizophrenia." (PMID 33656268, 2021). "Together, these findings indicated that Egr3 was regulated downstream of three proteins independently implicated in schizophrenia risk: NMDARs, NRG1 and CN." (PMID 29520222, 2018). "Egr3 is an immediate-early gene transcription factor implicated in schizophrenia susceptibility, and expressed at reduced levels in post-mortem brain tissue from schizophrenia patients." (PMID 30158860, 2018). "Single nucleotide polymorphisms (SNPs) in EGR3 are associated with schizophrenia, and EGR3 mRNA expression is decreased in the postmortem brains of schizophrenia patients compared with controls." (PMID 29459824, 2018). "Despite the paucity of published work on the role of NAB2 in the brain, the regulatory relationships between NAB2, EGR1 and EGR3 link this gene not only to other specific schizophrenia-associated genes, but also to the proposed pathway for illness association." (PMID 29520222, 2018). "Genetic association of EGR3 with schizophrenia has been shown in Chinese, Japanese and Korean populations, and more recently in a population of European descent." (PMID 29520222, 2018). "Our proposed biological pathway combines environment stress-responsive proteins EGR3, CN, and NMDARs, each of which are associated with schizophrenia susceptibility." (PMID 29520222, 2018). "The 8p chromosomal region, where EGR3 resides, is a long-recognized hub for schizophrenia associations." (PMID 29520222, 2018). "Studies investigating the potential role of EGR family genes on risk for psychiatric disorders have focused most on the schizophrenia; the most positive findings have been on early growth response gene 3 (EGR3)." (PMID 29459824, 2018). "In line with this theory, bioinformatic analyses have predicted EGR3 to be a central modulator of a regulatory network of microRNAs and transcription factors associated with schizophrenia." (PMID 29520222, 2018). "Our major findings were that EGR3 SNP rs1877670 was associated with schizophrenia in our population of EU cases and controls (p = 0.0078)." (PMID 26474411, 2015). "We have previously reported that Egr3-deficient (Egr3KO) mice display schizophrenia-like behavioral abnormalities that are reversible with antipsychotic treatment." (PMID 26474411, 2015). "In the EU replication study EGR3 SNP rs1877670 showed a significant association with schizophrenia (p = 0.0078)." (PMID 26474411, 2015). "It is also the first study reporting associations between SNPs in EGR3 and schizophrenia in an AA population." (PMID 26474411, 2015). "To date, three case-control and one family-based study have identified significant associations between SNPs in EGR3 and schizophrenia." (PMID 26474411, 2015). "The 8p chromosomal region, and indeed the specific location of EGR3 at 8p21.3, have been repeatedly associated with schizophrenia susceptibility, specifically in the AA population." (PMID 26474411, 2015). "EGR3 is one of these compelling susceptibility genes that have been associated with schizophrenia in various ethnic populations." (PMID 22276163, 2012). "In summary, our study provides evidence for the association of the EGR3 locus and schizophrenia in the Han Chinese population." (PMID 22276163, 2012).
schizophrenia (continued). "To further confirm or exclude the implication of EGR3 in association with schizophrenia, we performed a meta-analysis." (PMID 22276163, 2012). "In the current study, we found that SNP rs35201266 of EGR3 and several haplotypes comprised of rs35201266 were significantly associated with schizophrenia patients of Han Chinese origin." (PMID 22276163, 2012). "In summary, our study supports the association of EGR3 with schizophrenia in our Han Chinese sample, and further functional exploration of the EGR3 gene will contribute to the molecular basis for the complex network underlying schizophrenia pathogenesis." (PMID 22276163, 2012). "EGR3 is at the convergence of several signaling pathways, miRNA regulatory networks, adaptation to stress, and genetic susceptibility to schizophrenia." (PMID 20156358, 2010). "PPP3CC (encoding calcineurin catalytic γ subunit) is located very close to EGR3 on chromosome 8 and was reported to be associated with schizophrenia." (PMID 20156358, 2010). "Our hypothesis has subsequently been supported by studies showing both genetic association of EGR3 with schizophrenia, as well as decreased EGR3 gene expression in brains of schizophrenia patients and fibroblasts isolated from schizophrenia patients." (PMID 35941129, 2022). "Based on these findings, we hypothesized that EGR3 is a critical transcriptional regulator in a biological pathway essential for memory, synaptic plasticity, and risk for schizophrenia." (PMID 35941129, 2022). "We have hypothesized that dysfunction of Egr3 could disrupt the brain’s normal neurobiological response to stress, resulting in increased risk to develop mental illnesses such as schizophrenia and bipolar disorder." (PMID 29867393, 2018). "Furthermore, a bioinformatics analysis of the network of transcription factors and microRNAs associated with schizophrenia indicated EGR3 as a central gene in this regulatory network." (PMID 29459824, 2018). "A reduced expression of Egr3 is reported in the brains of schizophrenics and an allelic variant of the Egr3 locus confers increased likelihood of schizophrenia (albeit in an ethnicity-dependent-manner)." (PMID 30158860, 2018). "Bioinformatics approaches have identified Egr3 as a central gene in a network of transcription factors and microRNAs implicated in schizophrenia risk, as well as a master regulator of genes differentially expressed in the brains of bipolar disorder patients in two independent cohorts." (PMID 29867393, 2018). "We have previously reported that Egr3-deficient (-/-) mice have behavioral abnormalities consistent with animal models of mental illness, including schizophrenia and bipolar disorder, that are rescued by the antipsychotic medications used to treat these disorders." (PMID 29867393, 2018). "Interestingly, an association of SNPs in Egr3 and Arc with schizophrenia has been proposed as a biological pathway of environmentally responsive, synaptic plasticity-related, schizophrenia risk genes." (PMID 29321734, 2017). "Polymorphisms in the promoter of the gene encoding EGR3 are implicated in schizophrenia." (PMID 26738766, 2016). "EGR3 SNP rs35201266 has also been associated with prefrontal hemodynamic response to a verbal fluency test in both control and schizophrenia subjects of Japanese ethnicity, suggesting a relationship between EGR3 and cognitive function in a brain region implicated in schizophrenia." (PMID 26474411, 2015). "Single nucleotide polymorphisms (SNPs) in EGR3 are associated with schizophrenia in Japanese, Korean, and Han Chinese (CH) populations, and levels of EGR3 mRNA are reduced in post-mortem brain tissue from schizophrenia patients." (PMID 26474411, 2015). "Numerous findings suggest a role for the IEG EGR3 in schizophrenia susceptibility." (PMID 26474411, 2015). "We report that the EGR3 SNP rs1877670 is associated with schizophrenia in an EU population." (PMID 26474411, 2015).